FGF21 (fibroblast growth factor 21)
Diseases named in the same sentence as FGF21 in open-access papers (continued):
Sharing a sentence is not in itself a finding about the gene and the disease.
diabetes (continued). "Fibroblast growth factor 21 (FGF21), an endocrine hormone in the FGF family, plays a critical role in regulating metabolic homeostasis and has emerged as a therapeutic target for metabolic diseases, including Type 2 diabetes mellitus." (PMID 30068552, 2018). "While one study reported that the predictive utility of FGF-21 was as good as the oral glucose tolerance test (OGTT), the other study found that including FGF-21 did not improve diabetes prediction." (PMID 29021814, 2017). "FGF21 stimulates insulin secretion in ex vivo islets isolated from rodent models of diabetes, but does not affect insulin secretion from islets isolated from healthy mice." (PMID 28770320, 2017). "In the patients with diabetes, we found a non-significant increase in FGF-21 levels in the first 2 years, returning to values similar to baseline at the end of the study." (PMID 26986485, 2016). "Thus, the aim of the present study was to clarify the possible link between serum FGF21 levels and LEAD in diabetes patients." (PMID 25850006, 2015). "Circulating FGF21 levels also increase after RYGB surgery but it is not known if this outcome is also specific to patients that do not enter into diabetes remission." (PMID 25664662, 2015). "A common pattern emerged whereby patients that do not remit diabetes (T2D-NoR) displayed signifciantly higher expression levels for FGF21, HNF4α, CYP7A1, β-Klotho, GS, and FGFR4, compared to the No-T2D and T2D-R groups." (PMID 25664662, 2015). "The cardiac HKII expression was not affected by FGF21 deletion under basal conditions, but was significantly impaired by diabetes in FGF21KO diabetic mice at 2 and 4 months after diabetes onset." (PMID 25823710, 2015). "The cardiac PGC1α expression was not affected by FGF21 deletion under basal conditions, but was significantly attenuated by diabetes in FGF21KO diabetic mice at 4 months after diabetes onset." (PMID 25823710, 2015). "When combining high FGF21 with low FGF19 levels, 91% of Class III obese patients had diabetes." (PMID 25664662, 2015). "The effects of serum FGF21 concentrations on diabetes and diabetic retinopathy were assessed by conditional logistic regression analysis, after adjustment for the other parameters (HOMA-IR, insulin, HbA1c, FGF21, and glucose) by matching." (PMID 24895642, 2014). "Additionally we found that diabetes increased renal 3-NT, 4-HNE, and CTGF expression, which were also significantly suppressed by FGF21 treatment." (PMID 24349242, 2013). "In the present study, we found that diabetes has additional effects on FGF21 levels in CKD patients, which are supported by the fact that plasma FGF21 levels in CKD individuals with DM were significantly higher than those CKD patients without this complication." (PMID 21525989, 2011). "Serum FGF-21 levels correlated positively with triglycerides, fasting blood glucose, apolipoprotein B100, insulin and HOMA-IR but negatively with HDL-C and apolipoprotein A1 after adjusting for BMI, diabetes and hypertension." (PMID 21206918, 2010). "Metformin, an insulin‐sensitizing drug that is the first‐line treatment for type 2 diabetes mellitus (T2DM), may have a potential neuroprotective impact by up‐regulating the production of FGF21, which may prevent the onset of neurodegenerative diseases including MS." (PMID 40172524, 2025). "FGF21 protects the vascular endothelium and smooth muscle layers by inhibiting the NLRP3 inflammasome, and our previous research showed that FGF21 inhibits VSMC proliferation and migration through inhibition of the SYK-NLRP3 inflammasome pathway, alleviating diabetes-induced neointimal hyperplasia." (PMID 38733164, 2024). "We could not in our study however, observe any difference in FGF21 levels with regard to diabetes duration." (PMID 38932813, 2024).
diabetes (continued). "When investigating FGF21, Cystatin C, lipocalin-2, and MMP-9 in this study from diagnosis of type 1 diabetes over time, Cystatin C showed most promising results with increased values from diagnosis to follow-up and inverse correlation to HbA1c and duration of diabetes." (PMID 38932813, 2024). "Serum FGF21 levels were significantly higher in 2DM patients than those without diabetes." (PMID 37869250, 2023). "Moreover, basal FGF21 secretion, especially in response to insulin dose, in patients with type 1 diabetes mellitus (T1DM), has not been well examined." (PMID 35192641, 2022). "In addition, circulating FGF21 was elevated in MAFLD patients with diabetes compared to those without (p < 0.005)." (PMID 34141520, 2021). "Thus, increased FGF21 and elevated energy expenditure do not protect against hyperglycaemia and diabetes per se." (PMID 29550873, 2018). "Given the potential but still unknown influence of myokines on nutrient and energy metabolism, we aimed to evaluate the association of circulating levels of myostatin, myonectin, and FGF-21 with whole-body IR in individuals without known diabetes mellitus." (PMID 29445355, 2018). "However, FGF21 was not independently associated with the presence of SAP in a model where variables studied included gender, age, BMI, diabetes, and LDL-c." (PMID 30185439, 2018). "Similar mechanisms might also be at play in human fat cells: people with diabetes had higher methylation levels near the FGF21 gene compared to people without diabetes, and the degree of methylation was also inversely correlated with the levels of FGF21 mRNA." (PMID 29239299, 2017). "FGF21 prevents the onset of diet-induced diabetes, without changing body fat mass." (PMID 28770320, 2017). "The present results indicate that FGF-21 may be a biologically relevant substrate for FAP in humans, but not in mice and therefore, that FAP inhibitors may prove useful in the treatment of diabetes and metabolic disorders in humans by increasing the lifetime of FGF-21." (PMID 26962859, 2016). "In patients with diabetes, we could not find significant differences in FGF-21 concentrations, probably due to the limited sample size." (PMID 26986485, 2016). "Interestingly, it has been shown that FGF15/19 and FGF21 have potential roles in metabolic diseases, such as nonalcoholic fatty liver disease, bile acid diarrhea, cardiovascular disease and diabetes." (PMID 26931208, 2016). "We did not have available, paired, postoperative serum samples to determine whether the reported increase of FGF21 after RYGB surgery is specific to patients remitting or not remitting diabetes." (PMID 25664662, 2015). "Taken together, these data provide evidence that FGF21 and the FGF19-BA pathway are significantly perturbed in severe diabetes and could represent suitable targets for the development of a new class of treatments for diabetes provided that the pro-oncogenic effects of FGF19 could be curtailed." (PMID 25664662, 2015). "Circulating FGF21 level was independently associated with CIN (aOR: 4.66, 95% CI: 1.29–16.86, p = 0.019) and renal function decline (aHR: 7.98, 95% CI: 4.07–15.66, p < 0.001) whether diabetes was present or not." (PMID 30127382, 2018). "Nine biomarkers were positively associated with depressive symptoms in the total sample (CCL11/eotaxin, CCL25, CDCP1, FGF-21, IL-8, IL-10RB, IL-18, MMP-10, TNFRSF9; all p < 0.05) without interaction by diabetes type." (PMID 39799156, 2025). "The application of a half-life extended form of FGF21 (FGF21-PEG) has been demonstrated to normalize plasma glucose levels in streptozotocin-treated mice, a model of type 1 diabetes mellitus (T1DM), without reinstating pancreatic β-cell function." (PMID 38312833, 2024). "The results provide further support for the role of PTEN, BECN1, FGF21, Klotho, and CTGF in development albuminuric and non-albuminuric CKD in diabetes." (PMID 38540101, 2024).
diabetes (continued). "FF prevents diabetes-induced cardiac dysfunction, inflammation, and cardiac remodeling and increases the expression of FGF21 and SIRT1 in both patients with and without diabetes." (PMID 37754811, 2023). "One explanation for these findings is that none of the cats used in this study had marked metabolic dyscrasia or type 2 diabetes mellitus (T2DM), unlike the human and non-human primates in other studies treated with FGF21." (PMID 36756310, 2023). "Although previous clinical trials with pegozafermin and other FGF21 analogs have consistently demonstrated improvements in lipids in both healthy volunteers and patients with NASH or diabetes, FGF21 analogs have not been assessed in SHTG23,25–29." (PMID 37355760, 2023). "Of course, varying elevations in serum FGF21 and GDF15 levels also exist in non-neuromuscular diseases, including diabetes, liver diseases, kidney diseases, tumours, heart diseases, and respiratory diseases." (PMID 35498801, 2022). "In conclusion, we found elevated levels of serum FGF21 levels in PPGL and their relation to secondary diabetes mellitus, but not to the hypermetabolic state." (PMID 30959789, 2019). "FGF21 deletion had no obvious effects on cardiac CD36 expression under basal conditions, but diabetes significantly up-regulated CD36 expression in both WT and FGF21KO hearts." (PMID 25823710, 2015). "We found in the C57BL/6J mice that diabetes, but not STZ, strongly induced renal apoptosis, which was further enhanced in FGF21-KO mice." (PMID 24349242, 2013). "Interestingly, CKD patients recruited into this study with diabetes mellitus (DM) (1253±170.1 pg/ml, n = 68) had significantly higher plasma FGF21 levels (P = 0.0016) than those without DM (714±82.1 pg/ml, n = 132)." (PMID 21525989, 2011). "We performed a logistic regression analysis of the relation between serum levels of FGF-21 and CHD patients with and without diabetes and hypertension." (PMID 21206918, 2010). "The results provide further support for the role of PTEN, BECN1, FGF21, Klotho, and CTGF in the pathogenesis of diabetic kidney disease, and highlight the differences in the molecular pathways of albuminuric and non-albuminuric CKD in diabetes." (PMID 38540101, 2024). "In partial agreement with our study, an earlier study among 179 Chinese NAFLD patients with and without diabetes (68 NASH cases and 111 non-NASH cases) reported that the serum levels of several biomarkers, including FGF-21, were significantly higher in NAFLD patients compared with healthy controls." (PMID 38222178, 2023). "Moreover, hepatic expression levels of FGF21, CYP7A1, HNF4α, β-Klotho, FGFR4, and GS were higher in T2D patients that do not remit diabetes after RYGB surgery." (PMID 25664662, 2015). "Furthermore, we found that the diabetes, rather than STZ, significantly increased both plasma and renal TG levels in C57BL/6J mice, which was further aggravated in FGF21-KO mice." (PMID 24349242, 2013). "Furthermore, plasma FGF21 levels in CKD patients are significantly correlated with adverse lipid profiles and LVH, but not with LVMI after adjustment for age, gender, BMI and diabetes." (PMID 21525989, 2011). "In addition, using liver wedge biopsies taken during surgery, we compared the expression levels of FGF21 and of key genes in the FGF19-BA pathway between diabetic and non-diabetic patients and also between diabetic patients that remit or do not remit diabetes after RYGB surgery." (PMID 25664662, 2015). "However, diabetes and hypertension are unlikely to be a primary factor for the increment of FGF-21 in CHD patients, since CHD patients without diabetes and hypertension had significantly higher FGF-21 levels than normal controls." (PMID 21206918, 2010). "Here, despite high levels of FGF21 in diabetic control rats, elevated levels of VEGF and TGF-β may be due to several factors contributing to increased production of angiogenic factors in uncontrolled diabetes, and FGF21 alone may not be sufficient in prevention." (PMID 38584657, 2024).
type 2 diabetes (287 papers, 2011 to 2026). "Direct effects indicate that FGF21 has a causal relationship with Type 2 diabetes (OR=0.787, 95%CI (0.646-0.960), P=0.0179) and Basal metabolic rate (OR=0.962, 95%CI(0.935-0.990), P=0.0091)." (PMID 39296716, 2024). "In the causal relationship between FGF21 and osteoporosis, the mediating effects of Type 2 diabetes and Basal metabolic rate were 14.96% and 12.21%, respectively." (PMID 39296716, 2024). "Elevated levels of FGF-21 (OR = 0.77, 95% CI = 0.60-0.98, P-value = 0.0311) reduced the incidence of neurological complications in type 2 diabetes, although this association was only nominally significant." (PMID 38606083, 2024). "In contrast, FGF21 level is positively associated with metabolic conditions such as type 2 diabetes, insulin resistance and hsCRP, which is probably an adaptive response." (PMID 39341924, 2024). "The results of mediating MR Analysis showed that the causal relationship between FGF21 and osteoporosis was mediated by Type 2 diabetes and Basal metabolic rate, and the proportion of mediating effect was 14.96% and 12.21%, respectively." (PMID 39296716, 2024). "In conclusion, the expression of IDOL in CD14+ monocytes was decreased in subjects with type 2 diabetes and was associated with glycemia and serum FGF21 concentration." (PMID 37094639, 2023). "In conclusion, the expression of IDOL in CD14+ monocytes was decreased in type 2 diabetes and was associated with glycemia and serum FGF21 concentration." (PMID 37094639, 2023). "In general, our study identified the important value of FGF21 in the risk assessment of newly diagnosed type-2 diabetes in southern Chinese populations." (PMID 37658393, 2023). "FGF-21 is elevated in obese subjects and is independently associated with the development of type 2 diabetes." (PMID 37170273, 2023). "First, this cross-sectional study was unable to establish any causal relationships between FGF-21 and the development of type-2 diabetes." (PMID 37658393, 2023). "In humans, circulating FGF21 levels are elevated in coronary heart disease and atherosclerosis and are related to a high risk of cardiovascular events in patients with type 2 diabetes." (PMID 35069790, 2022). "FGF21 exerts this protective role against DCM in type 2 diabetes employing AMPK-associated anti-oxidative (AMPK-AKT2-NRF2) and lipid-diminishing (AMPK-ACC-CPT1) pathways." (PMID 34095143, 2021). "Evidences also showed the independent association of FGF21 levels with urinary albumin excretion (UAE) or albuminuria in type 2 diabetic patients." (PMID 31205953, 2019). "In conclusion, our data indicated that genetic variants adjacent to FGF21 were associated with eGFR in subjects with type 2 diabetes." (PMID 31205953, 2019). "Newly emerging risk markers of type 2 diabetes (fetuin A, fibroblast growth factor 21 (FGF-21), interleukin-1 receptor antagonist (IL-1ra) and omentin) were considered as secondary outcomes." (PMID 28604592, 2017). "The positive association between FGF-21 and incident type 2 diabetes found in the current study is in accordance with previous studies." (PMID 29021814, 2017). "In conclusion, circulating CTRP1 levels are increased in subjects with type 2 diabetes and are positively associated with circulating FGF21 levels." (PMID 27313611, 2016). "In humans, circulating FGF21 levels are elevated in coronary heart disease and atherosclerosis, and are associated with a higher risk of cardiovascular events in patients with type 2 diabetes." (PMID 26379627, 2015). "If BMI was replaced by WC in models of both genders (Model 2), FGF21 remained as a significant impact factor associated with subclinical atherosclerosis in type 2 diabetes in both men and women (P = 0.026 and P = 0.037, respectively)." (PMID 26047614, 2015). "Our study, which is focused on the early stage of atherosclerosis in newly diagnosed type 2 diabetes patients, suggests that FGF21 is linked to the initiation and formation of atherosclerosis." (PMID 26047614, 2015).
type 2 diabetes (continued). "One possibility is that bone mass loss in MR mice on HFD is associated with increased levels of FGF21, a hepatokine shown to reverse obesity and type 2 diabetes via Pparγ signaling mechanisms." (PMID 23236485, 2012). "These low levels may also reflect a possible impairment in FGF21 adaptive responses as observed in other age-associated diseases including Alzheimer’s and type II diabetes." (PMID 40788112, 2025). "Genetic prediction of FGF-21 (OR = 0.87, 95% CI = 0.81-0.93, P-value = 9.77e-05) and hGDNF (OR = 0.96, 95% CI = 0.95-0.98, P-value = 2.77e-05) per a 1-SD increase correspondingly reduced the risk of type 2 diabetes." (PMID 38606083, 2024). "The relationship between FGF21 and basal metabolic rate has not been reported at present, which may be related to the reduced risk of type 2 diabetes caused by overexpression of FGF21, and more studies are needed to clarify it in the future." (PMID 39296716, 2024). "Elevated FGF21 levels have also been demonstrated among patients with type II diabetes, and it is believed that this factor may be associated with a significant increase in the risk of set-associated complications in this group of patients." (PMID 38139126, 2023). "Pegbelfermin (BMS-986036), a PEGylated FGF21 analog has been used in obese patients with type 2 diabetes predisposed to fatty liver, resulting in an improvement of the lipid profile, of fibrosis biomarkers and adiponectin levels, in the presence of mild adverse events." (PMID 36500979, 2022). "Strong evidences indicate that FGF21 treatment in vivo effectively reduces renal structure and function damage caused by type 1 and type 2 diabetes, improves renal tubular epithelial cells injury, and significantly decreases the expression of inflammatory reaction and oxidative damage factors." (PMID 34773993, 2021). "Moreover, in type 2 diabetes patients, the level of serum FGF21 is significantly linked to the occurrence of nephropathy, proteinuria, and the progression of end-stage renal disease (ESRD)." (PMID 34675822, 2021). "Besides, previous studies have demonstrated that there was a association between hypoxia and FGF21 regulation in many diseases such as type 2 diabetes with early renal injury, pulmonary hypertension, and cerebral disease." (PMID 32922298, 2020). "A prospective study demonstrated an independent association between elevated serum FGF21 levels and eGFR decline; thus, the circulating FGF21 level was proposed as a predictor for progressive kidney disease in subjects with type 2 diabetes and normoalbuminuria." (PMID 31205953, 2019). "Moreover, plasma FGF21 levels have been linked to a higher risk of cardiovascular events in patients with type 2 diabetes." (PMID 26379627, 2015). "Second, this phenomenon provides a mechanism accounting for the increase in plasma FGF21 concentration and hepatic FGF21 mRNA abundance observed in animals and patients with type 2 diabetes, a condition that is associated with an elevation in the plasma concentration of both glucagon and insulin." (PMID 24733293, 2014). "In addition, hepatic 5-HTR2A and 5-HTR2B signaling might contribute to hepatic fibroblast growth factor-21 (FGF21) production and the pathophysiological mechanisms of type 2 diabetes (T2D) and metabolic dysfunction-associated fatty liver disease (MAFLD)." (PMID 39926388, 2025). "Our study suggests that the overexpression of FGF21 may lead to a decrease in bone mineral density and increase the risk of osteoporosis, and the effect of FGF21 on osteoporosis may be mediated through type 2 diabetes and basal metabolic rate." (PMID 39296716, 2024). "Our study suggests that the increased expression of FGF21 may lead to the decrease of bone mineral density and increase the risk of osteoporosis, while type 2 diabetes and basal metabolic rate may play a mediating role in the relationship between FGF21 and osteoporosis." (PMID 39296716, 2024).